IGF2 (insulin like growth factor 2)
Description:
The insulin-like growth factors possess growth-promoting activity (By similarity). Major fetal growth hormone in mammals. Plays a key role in regulating fetoplacental development. IGF2 is influenced by placental lactogen. Also involved in tissue differentiation. In adults, involved in glucose metabolism in adipose tissue, skeletal muscle and liver (Probable). Acts as a ligand for integrin which is required for IGF2 signaling. Positively regulates myogenic transcription factor MYOD1 function by facilitating the recruitment of transcriptional coactivators, thereby controlling muscle terminal differentiation (By similarity). Inhibits myoblast differentiation and modulates metabolism via increasing the mitochondrial respiration rate (By similarity). Preptin undergoes glucose-mediated co-secretion with insulin, and acts as a physiological amplifier of glucose-mediated insulin secretion. Exhibits osteogenic properties by increasing osteoblast mitogenic activity through phosphoactivation of MAPK1 and MAPK3.
Synonyms: IGF-II; FLJ44734; C11orf43; GRDF; PP9974; SRS3
Tractability: Antibody: a drug acting on it is in phase 2 or 3 trials; UniProt places it where antibodies can reach, with high confidence; its Gene Ontology location is reachable by antibodies, with high confidence; UniProt predicts a signal peptide or a membrane-spanning region.
Target class: Secreted protein
Gene: Protein-coding gene on chromosome 11 (2,129,112 to 2,158,391, reverse strand). Ensembl gene ENSG00000167244.
Subcellular location: Secreted
Subcellular location (Human Protein Atlas): Golgi apparatus; Predicted to be secreted
Pathways (Reactome):
Signal Transduction: IRS-related events triggered by IGF1R; SHC-related events triggered by IGF1R; Signaling by Type 1 Insulin-like Growth Factor 1 Receptor (IGF1R)
Chromatin organization: CHD6, CHD7, CHD8, CHD9 subfamily
Hemostasis: Platelet degranulation
Metabolism of proteins: Regulation of Insulin-like Growth Factor (IGF) transport and uptake by Insulin-like Growth Factor Binding Proteins (IGFBPs)
Gene Ontology:
Molecular function: growth factor activity; insulin receptor binding; insulin-like growth factor receptor binding; integrin binding; protein binding; protein serine/threonine kinase activator activity; receptor ligand activity; hormone activity
Biological process: positive regulation of activated T cell proliferation; positive regulation of cell population proliferation; positive regulation of insulin receptor signaling pathway; positive regulation of MAPK cascade; positive regulation of mitotic nuclear division; positive regulation of phosphatidylinositol 3-kinase/protein kinase B signal transduction; embryonic placenta development; embryonic placenta morphogenesis; genomic imprinting; in utero embryonic development; insulin receptor signaling pathway; negative regulation of muscle cell differentiation; negative regulation of transcription by RNA polymerase II; positive regulation of glycogen biosynthetic process; regulation of DNA-templated transcription; regulation of muscle cell differentiation; insulin-like growth factor receptor signaling pathway; osteoblast differentiation; positive regulation of organ growth; positive regulation of skeletal muscle tissue growth
Cellular component: extracellular region; platelet alpha granule lumen
Genetic constraint (gnomAD): Loss-of-function variants: 2 observed, 12.69 expected, observed/expected ratio (o/e) 0.16, 90% interval 0.063 to 0.5. The upper end of that interval is the gene's LOEUF score, 0.5, which puts it in group 2 of 6, group 1 being the genes least tolerant of losing a copy. Missense variants: 209 observed, 265.63 expected, observed/expected ratio (o/e) 0.79, 90% interval 0.7 to 0.88. Synonymous variants: 105 observed, 110.38 expected, observed/expected ratio (o/e) 0.95, 90% interval 0.81 to 1.12.
Gene-disease validity (ClinGen):
ClinGen rates the evidence that IGF2 causes each of these diseases.
Silver-Russell syndrome 3 (autosomal dominant): Definitive.
Homologues: Orthologues: chimpanzee IGF2 (100% identical), macaque IGF2 (96% identical), dog IGF2 (92% identical), guinea pig IGF2 (87% identical), rat Igf2 (85% identical), mouse Igf2 (84% identical), tropical clawed frog igf2 (53% identical), zebrafish igf2b (49% identical), zebrafish igf2a (43% identical). Paralogues in human: IGF1 (31% identical), INS (19% identical).
Diseases named in the same sentence as IGF2 in open-access papers:
IGF2 is named in the same sentence as 489 diseases in open-access papers, as found by Europe PMC text mining. Sharing a sentence is not in itself a finding about the gene and the disease. The quoted sentences say what the papers report.
breast carcinoma (168 papers, 1995 to 2025). "For example, high birth weight is positively associated with an increased risk of breast cancer, particularly among premenopausal women, potentially resulting from increased IGF2 expression due to loss of imprinting at the H19/IGF2 locus." (PMID 41256926, 2025). "CAFs exert pro-tumorigenic as well as anticytotoxic effects on breast cancer cells associated with the secretion of IGF2." (PMID 38892104, 2024). "The association between increased IGF2 expression and poorer prognosis is well established, as shown by the elevated mortality in breast cancer, shorter recurrence times in oesophageal cancer, and faster progression in chronic myeloid leukemia." (PMID 37393293, 2023). "Recent studies on breast cancer (BC) have revealed a bidirectional regulation between IGF2 and the inhibitor of DNA-binding 1 (Id1) that is linked to cell stemness." (PMID 36672737, 2023). "High IGF2 gene expression in cancer-associated fibroblasts from luminal breast carcinomas is significantly related to a shortened relapse-free survival." (PMID 35692369, 2022). "Elevated expression of IGF-2 is also associated with increased risk of breast cancer development and has been implicated in disparities in breast cancer risk and survival outcomes in African American women." (PMID 36556357, 2022). "In breast cancer, 91H lncRNA prevents DNA methylation on the maternal allele at the H19/IGF2 locus, and thereby increases aggressive phenotype of breast cancer cells." (PMID 32929060, 2020). "Previous studies have found associations between polymorphisms within the IGF2 gene relating to birth weight, progression of ovarian and breast cancer, and one such study suggested parent of origin effects." (PMID 26496499, 2015). "Of note, IGF-2, known to associate with breast cancer promotion, is expressed in TNBC and neighboring cells in archival clinical specimens and stimulates increased levels of ERβ mRNA in TNBC cells." (PMID 25874233, 2015). "The SNP lies close to the H19/IGF2 imprinted region, and the association of breast cancer with rs3817198 has been reported to be restricted to the paternally inherited allele." (PMID 23544014, 2013). "Loss of imprinting of IGF2 has also reported in half of 47 breast cancer tissues in one study in China, and another study conducted in India reported biallelic expression in 3 of 10 breast tumor samples." (PMID 23409079, 2013). "The purpose of this study was to explore the risk factors for breast cancer and establish the expression rate of IGF-2 in female patients." (PMID 22662119, 2012). "Elevated circulating IGF-1 levels have been significantly associated with an increased risk of breast cancer, while the evidence for IGF-2 is less clear." (PMID 22662119, 2012). "The purpose of the study was therefore to explore risk factors for breast cancer development and to identify IGF-2 expression rate in invasive breast cancer in women of Wuhan city." (PMID 22662119, 2012). "Overexpression of IGF-2 was also positively correlated with increased risk of breast cancer, nodal positivity and higher tumor grade." (PMID 23148692, 2012). "Several studies have shown that prosaposin, a regulator of estrogen receptor alpha, promotes breast cancer growth and that IGFs play an important role in cancer development and specifically and increased IGF-2 production has been linked with cancer development and progression in many conditions." (PMID 39580456, 2024). "Both of these molecular defects result in overexpression of IGF2, which may be associated with tumorigenesis in various subtypes of breast cancer and may cause juvenile fibrous and lobular breast tumors, as in the current case." (PMID 38514513, 2024). "HMGA1P6 and HMGA1P7, two pseudogenes of HMGA1 competing for endogenous RNA, can also lead to cancer when they are dysregulated, and the expression of HMGA1P7 is related to the levels of H19 and IGF2 in breast cancer, which is linked to the high double strand breaks in breast cancer cells." (PMID 35864955, 2022).
breast carcinoma (continued). "Another lncRNA, named 91H which located at the H19/IGF2 locus and transcribed in H19 antisense orientation, is overexpressed in breast cancer and prevent the maternal allele at the H19/IGF2 locus from DNA methylation, by this mechanism to induce overexpression of oncogenic H19." (PMID 36533073, 2022). "In addition, IGF-2 has been recently implicated in a positive feedback circuit as a critical mechanism to increase stemness and maintain breast cancer cells." (PMID 33114046, 2020). "The IGF2 genetic variants can influence the death risks of breast cancers with BRCA1/2 mutations." (PMID 28415743, 2017). "Since our data focused only on colon cancer therapy, further studies are required to explore the use of these vectors to gene therapy for other types of cancer that are loss of IGF2 imprinting, such as hepatoma, lung cancer, breast cancer, leiomyosarcoma, osteosarcoma, leukemia and Wilms’ tumor." (PMID 23900345, 2013). "A number of studies have shown consistently the loss of imprint of IGF-2, which are associated with increased risk of several cancers, including those cutaneous melanoma, laryngeal squamous cell carcinoma, human meningiomas and breast cancer." (PMID 22662119, 2012). "Other proposed mechanisms include (i) a joint effect of insulin-like growth factor 1(IGF-1) and estrogens on breast cancer risk; (ii) a potential link between loss of genetic imprinting of IGF-2, which could play a role in fetal growth and breast cancer risk." (PMID 23061041, 2012). "Besides, H19 mutation may produce antisense RNA 91H accumulating in breast cancer cells and regulate the expression of insulin growth factor 2 (IGF2), thereby affecting oncogene and tumor suppressor gene expression." (PMID 36588790, 2022). "The IGF-2, an imprinted gene with paternal allele expressed and maternal allele silenced, is an important autocrine growth factor in tumors due to its mitogenic and antiapoptotic functions mediated by receptor, which is suggestive of its role in the development of breast cancer." (PMID 22662119, 2012). "CAF-derived IGF2 secretion activates IGF1R signaling in breast cancer cells by increasing the EMT as well as the in vitro and in vivo growth and migration." (PMID 38892104, 2024). "This in turn, led to the overexpression of IGF2 and a decrease in the sensitivity of breast cancer cells." (PMID 38505423, 2024). "In breast cancer studies, bidirectional regulation between autocrine IGF2 and inhibitor of DNA-binding 1 (Id1) promotes tumor stemness." (PMID 38887298, 2024). "EO771 mammary tumor cells or MC38 colon adenocarcinoma cells were implanted into Igf2–/– mice and WT mice." (PMID 39545420, 2024). "Blocking IGF2 signaling by picropodophyllin reduced the proliferative effect of pericytes on breast cancer cells and reduced the size of brain tumors in mice inoculated with triple negative breast cancer." (PMID 37190188, 2023). "FOXO3a accelerated the trastuzumab resistance of HER2-positive breast cancer through targeting and up-regulating IGF2/IGF-1R/IRS1 signaling." (PMID 37529418, 2023). "Related studies have shown that IGF-1 and IGF-2 are highly expressed in a variety of malignant tumors, suggesting that they are closely related to the occurrence and development of breast cancer." (PMID 35845730, 2022). "Many studies have established that IGF-1 and IGF-2 increase proliferation and growth of breast carcinoma cells in vitro, and mouse models reveal that tumor growth in distal tissues is enhanced by signaling through the IGF-1R." (PMID 36556357, 2022). "Autocrine or paracrine loops of overexpressed IGF-2/IR-A are established in thyroid cancer and breast cancer cells." (PMID 36358907, 2022). "In conclusion, our study investigated the biological role of miR-98-5p and IGF2 in HER2 positive breast cancer." (PMID 34837929, 2021). "Our findings provide several insights into our understanding of the molecular basis of IGF2/IGF-1R/IRS1 signaling activation in Herceptin-resistant breast cancer." (PMID 33976188, 2021).
breast carcinoma (continued). "The insulin receptor isoform A (IR-A), a dual receptor for insulin and IGF2, plays a role in breast cancer (BC) progression and metabolic reprogramming." (PMID 34206590, 2021). "In recent study, researchers found that IGF2/IGF-1R/IRS1 signaling conferred Herceptin resistance in HER2-positive breast cancer." (PMID 34837929, 2021). "Accordingly, in breast cancer cells, IGF2BP1 knockdown determined increased mRNA expression for IGF2 associated with inhibition of cell proliferation." (PMID 33673232, 2021). "Our results provide a new viewpoint to better understanding the molecular mechanisms of IGF2 mediated signaling pathway activation in Herceptin resistant breast cancer." (PMID 34837929, 2021). "According to the TCGA breast cancer database, IGF2 expression level was significantly correlated with the HER2 status (Immunohistochemical type or gene PAM50 type)." (PMID 34837929, 2021). "First, Herceptin-resistant breast cancer cells over-produced IGF2, triggering autocrine activation of the IGF-1R signaling, which required IRS1 expression." (PMID 33976188, 2021). "Another key factor for maintenance of breast cancer stem cells, IGF2, is also expressed by breast CAF." (PMID 34439387, 2021). "Overexpression of IGF2 increases sphere forming activity and in vivo tumorigenicity of breast cancer cells." (PMID 33293585, 2020). "We propose that methylation of DVDMR represents a novel epigenetic biomarker that determines the levels of IGF2 protein expression in breast cancer." (PMID 33216823, 2020). "Accordingly, IGF2 expression levels were lower in paclitaxel sensitive breast cancer cells than in paclitaxel resistant breast cancer cells in GSE90564 (p-value < 0.05)." (PMID 33221769, 2020). "In the tumorigenesis of breast cancer, miR-100 expression decreases, which upregulates IGF-2 to facilitate the cancer progression." (PMID 32399056, 2020). "Proliferation rate of breast cancer cells in conditioned media of Igf2‐silenced pericytes was similar to control cells, or cells cultured in pericyte‐conditioned media in the presence of PPP." (PMID 32534480, 2020). "miR-100 was found to be downregulated in breast cancer cells, which led to an increase in the insulin-like growth factor 2 (IGF2) expression." (PMID 32040529, 2020). "IGF2 is essential in breast differentiation, lactation, tumor growth, and in breast cancer (BC) development and progression." (PMID 33216823, 2020). "We aimed to characterize the metabolic impact of IR-A and its ligand insulin like growth factor 2 (IGF2) in human breast cancer (BC) cells." (PMID 31480557, 2019). "For example, a constitutive YAC transgenic Igf2r gain of function model was shown to rescue Thp (Igf2r loss of function), and also mammary tumour progression in an Igf2 induced mammary tumour model." (PMID 31388182, 2019). "Using the cancer genome atlas database we also found that increased gene expression of Igf-1, Igf-2, and the M2-like macrophage markers cd163 and mrc1 positively correlates with reduced survival in breast cancer patients." (PMID 29367764, 2018). "Here, we report that in breast carcinoma cells, the insulin-like growth factor 2 messenger RNA binding protein (IMP1) binds to lncRNA urethral carcinoma-associated 1 (UCA1) and suppresses the UCA1-induced invasive phenotype." (PMID 29669595, 2018). "In breast cancer, IGF-2 is secreted by both epithelial and stromal cells and binds and activate both IR and IGF-1R." (PMID 30453495, 2018). "So, it is very clear that IGF2 plays an important role in breast cancer proliferation and drug resistance." (PMID 28523716, 2017). "In summary, this study demonstrates that DDR1 associates with the IR, enhances the activation of IR downstream signaling and the mitogenic and pro-invasive effects of insulin and IGF-2 in breast cancer cells." (PMID 28591735, 2017). "Breast cancer cells were treated with IGF2 (0, 5, 10, 50 and 100 ng/ml) and cell proliferation was assayed by MTT method." (PMID 28523716, 2017).